TM4SF1 (transmembrane 4 L six family member 1)
Diseases named in the same sentence as TM4SF1 in open-access papers (continued):
Sharing a sentence is not in itself a finding about the gene and the disease.
pancreatic cancer (18 papers, 2014 to 2024). "Similar result was also obtained in the study that showed contribution of TM4SF1 loss to the invasion and migration of pancreatic cancer cells." (PMID 29665316, 2018). "This is different from cancers such as muscle‐invasive bladder cancer 11, pancreatic Cancer 12, 13, and glioma 14 where overexpression of TM4SF1 is linked to poor prognosis of these cancers." (PMID 29665316, 2018). "Together, these results indicated that TM4SF1-induced invadopodia formation and function in pancreatic cancer cells were associated with the expression of DDR1." (PMID 28368050, 2017). "Next, we analyzed the effects of stably silencing TM4SF1 on pancreatic tumors developed in immuno-deficient mice." (PMID 26709920, 2015). "Loss of TM4SF1 contributes to the invasion and migration of pancreatic cancer cells." (PMID 29665316, 2018). "Cao, Yang observed high expression of TM4SF1 protein in pancreatic tumor tissues as compared to normal pancreatic tissues and chronic pancreatitis tissues." (PMID 36678607, 2023). "This family has been found to have multiple roles in tumor development, and family member TM4SF1 has been reported to play an important role in a variety of tumors including lung, prostate, breast, liver, bladder, and pancreatic cancers." (PMID 36209368, 2022). "In pancreatic cancer, a novel pathway including TM4SF1/DDR1/MMP2 and 9 enhances invadosome formation and activity, thereby enhancing cell migration and invasion capabilities." (PMID 33917302, 2021). "The microRNAs miR-206 and miR-141 were shown to inhibit metastasis of triple-negative breast cancer and pancreatic cancer by negatively regulating TM4SF1 by targeting its 3′-untranslated region." (PMID 33015133, 2020). "Another study showed that decreased TM4SF1 expression enhanced the migration and invasion of pancreatic tumor cells in vitro." (PMID 33015133, 2020). "In pancreatic cancer, TM4SF1 has been shown to promote metastasis and cell motility be inducing invadopodia and regulating MMP activity." (PMID 30897168, 2019). "Originally identified as a tumor-specific antigen, TM4SF1 has been reported to be over-expressed in many epithelial cancers, such as pancreatic cancer, prostate cancer, liver cancer, and especially lung cancer." (PMID 31142317, 2019). "Studies have shown that TM4SF1 is higher in pancreatic cancer tissues and cell lines than the control." (PMID 29665316, 2018). "Our previous studies found that TM4SF1 was highly expressed in human pancreatic cancer tissues and various pancreatic cancer cell lines." (PMID 28368050, 2017). "Our study investigated that when overexpressed DDR1 in TM4SF1-silenced cells, the number of pancreatic cancer cells with invadopodia and the expression of MMP2 and MMP9 were increased." (PMID 28368050, 2017). "In pancreatic cancer tissues, qRT-PCR and scatter plots analysis further determined that TM4SF1 had a correlation with DDR1." (PMID 28368050, 2017). "We further analyzed and plotted TM4SF1 mRNA expression levels against the levels of DDR1 in pancreatic cancer tissue." (PMID 28368050, 2017). "Transmembrane-4-L-six-family-1(TM4SF1), a four-transmembrane L6 family member, is highly expressed in various pancreatic cancer cell lines and promotes cancer cells metastasis." (PMID 28368050, 2017). "TM4SF1 expression is also elevated in lung cancer, pancreatic cancer, liver cancer, and cervical cancer, leading to its classification as a tumor-associated antigen." (PMID 27153056, 2016). "The mRNA expression of TM4SF1 was higher in seven pancreatic cancer cell lines than in HPDE cell lines." (PMID 26709920, 2015). "We further investigated TM4SF1 mRNA expression in seven pancreatic cancer cell lines and HPDE cells." (PMID 26709920, 2015). "Future efforts should be devoted to understanding the mechanisms and pathways involved in the effects of TM4SF1 expression on chemoresistance of pancreatic cancer." (PMID 26709920, 2015).
pancreatic cancer (continued). "We evaluated that TM4SF1 was a putative target for gemcitabine resistance in pancreatic cancer cells." (PMID 26709920, 2015). "The cell proliferation and apoptosis were obtained to investigate the sensitivity to gemcitabine of pancreatic cancer cells after silencing TM4SF1 in vitro." (PMID 26709920, 2015). "The expression of TM4SF1 was evaluated in pancreatic cancer cell lines and human pancreatic duct epithelial (HPDE) cell lines by quantitative RT-PCR." (PMID 26709920, 2015). "The previous research revealed that TM4SF1 was involved in the development of pancreatic cancer and inhibited cells migration and invasion." (PMID 26709920, 2015). "In vivo, we used orthotopic pancreatic tumor models to investigate the effect of proliferation after silencing TM4SF1 by a lentivirus-mediated shRNA in MIA PaCa-2 cell lines." (PMID 26709920, 2015). "In vivo, silencing of TM4SF1 in MIA PaCa-2 cell lines increased the effectiveness of gemcitabine-based treatment in orthotopic pancreatic tumor models evaluated using noninvasive bioluminescent imaging." (PMID 26709920, 2015). "In previous profiling studies, TM4SF1 mRNA expression was elevated in pancreatic tumors and cancer cell lines." (PMID 26709920, 2015). "Down-regulation of transmembrane-4-L-six-family-1 (TM4SF1) is involved in mR-141-inhibited pancreatic cancer cell invasion and migration." (PMID 24992595, 2014). "Furthermore, TM4SF1 has been well-documented for its ability to initiate carcinogenesis in hepatocellular carcinoma, ovarian cancer, pancreatic cancer, and other malignancies." (PMID 38762481, 2024). "However, using TM4SF1 as a potential prognostic marker should be approached with caution, considering the specific type of pancreatic cancer." (PMID 36678607, 2023). "In recent years, both TM4SF18 and TM4SF1 are overexpressed in pancreatic cancer." (PMID 36209368, 2022). "In pancreatic cancer, TM4SF1-induced migration and invasion require DDR1." (PMID 33917302, 2021). "In addition, silencing of TM4SF1 decreased the odds of lung and liver metastases in orthotopic pancreatic cancer." (PMID 33015133, 2020). "In addition, it was also found that PAX2 transcriptional factor can bind to the promoter of previously reported transmembrane-domain family TM4SF1, a gene that played a role in gemcitabine resistant pancreatic cancer." (PMID 31622355, 2019). "Knockdown of TM4SF1 inhibited the migration and invasion of pancreatic cancer cells." (PMID 29665316, 2018). "To examine whether TM4SF1 regulated DDR1 expression in pancreatic cancer cell lines, we transfected siRNA into cells and found that the down-regulation of TM4SF1 could decrease the mRNA and protein expression levels of DDR1 in PANC-1 and AsPC-1." (PMID 28368050, 2017). "Here, we wondered whether TM4SF1 expression might affect the formation and function of pancreatic cancer cell invadopodia." (PMID 28368050, 2017). "The has-mir-141 could downregulate the expression of TM4SF1 to inhibit the pancreatic cancer cells’ migration and invasion." (PMID 27766936, 2016). "In conclusion, our study described that silencing of TM4SF1 sensitized pancreatic cancer cells via downregulating ABCB1 and ABCC1 to kill by treatment with gemcitabine may be of particular translational significance." (PMID 26709920, 2015). "In our study, we provided the evidence that TM4SF1 was more highly expressed in pancreatic cell lines than in normal pancreatic epithelial (HPDE) cells and gemcitabine resistance in pancreatic cancer cells could result from the expression of TM4SF1." (PMID 26709920, 2015). "In the present study, we sought to determine whether TM4SF1 could confer pancreatic cancer with the ability to gemcitabine resistance.We found that TM4SF1 was highly expressed in gemcitabine-resistance pancreatic cancer cell lines." (PMID 26709920, 2015). "So, we evaluated whether TM4SF1 induced the expressions of MDR genes to affect gemcitabine sensitivity in pancreatic cancer cells." (PMID 26709920, 2015).
pancreatic cancer (continued). "Thus, we hypothesized that TM4SF1 might collaborate with DDR1 involved in the formation of invadopodia which had the ability to degrade ECM to regulate pancreatic cancer metastasis." (PMID 28368050, 2017). "Thus, the goal of this study was to investigate whether TM4SF1-overexpressing pancreatic cancer cell lines are involving in gemcitabine resistance and to delineate the mechanism." (PMID 26709920, 2015). "In vitro, reduced TM4SF1 expression after TGF-ß1-induced EMT enhanced the migration and invasion of pancreatic cancer cells partially via decreased E-cadherin expression." (PMID 33015133, 2020). "The co-IP assays result and a positive correlation between TM4SF1 and DDR1 expression of pancreatic cancer tissues further provided the evidence of this interaction." (PMID 28368050, 2017). "Collectively, our study provides a novel regulatory pathway involving TM4SF1, DDR1, MMP2 and MMP9, which promotes the formation and function of invadopodia to support cell migration and invasion in pancreatic cancer." (PMID 28368050, 2017). "Tks5, an adaptor protein required for invadopodia formation, was also used to investigate the role of TM4SF1 and DDR1 in pancreatic cancer cells." (PMID 28368050, 2017). "Both TM4SF1 and DDR1 are overexpressed in pancreatic cancer and related with metastasis development." (PMID 28368050, 2017). "We next investigated the role of TM4SF1 and its relationship with DDR1 in pancreatic cancer tissues, we measured the mRNA expression levels of TM4SF1 and DDR1 in 20 pairs of pancreatic cancer tissue samples." (PMID 28368050, 2017). "Thus, TM4SF1 may be a promising target to overcome the chemoresistance of pancreatic cancer." (PMID 26709920, 2015). "The GO terms reported in PDACA1 using SPCS related more to pancreatic cancer and to the role of TM4SF1 than the non-smoothed data and the two one-factor smoothed data." (PMID 35380614, 2022). "Therefore, further studies in our laboratory will be focused on the function of TM4SF1, DDR1 and integrins in pancreatic cancer cells contacting with collagen." (PMID 28368050, 2017). "Quantitative RT-PCR analysis indicated that all pancreatic cancer cell lines expressed of TM4SF1 to a greater extent than did the non-transformed HPDE cells." (PMID 26709920, 2015). "In vivo, cells lacking TM4SF1 had reduced pancreatic tumor growth and increased responsiveness to treatments with gemcitabine." (PMID 26709920, 2015). "In this study, we observed that silencing of TM4SF1 decreased the number of cells with invadopodia and matrix degradation index in PANC-1, indicating that TM4SF1 efficiently regulated the formation and function of invadopodia to degrade ECM during pancreatic cancer cell migration and invasion." (PMID 28368050, 2017).
lung carcinoma (16 papers, 2007 to 2024). "Previous studies have shown that high expression of TM4SF1 was an independent risk factor for poor outcomes in lung cancer." (PMID 38206300, 2024). "The Human Protein Atlas database confirmed in both lung adenocarcinoma (p = 0.0017) and lung cancers, including both squamous cell cancer and adenocarcinoma (p = 0.00274), high TM4SF1 expression was associated with poor patient survival)." (PMID 31142317, 2019). "Together, these findings indicate that high TM4SF1 expression, an age over 80, a former smoking habit are risk factors for poor patient outcome in lung cancer." (PMID 31142317, 2019). "This antigen is known to be highly expressed in several cancer types, including CRC, and increased level of TM4SF1 has been associated with development of metastases and poor clinical outcome in patients with lung cancer." (PMID 17201907, 2007). "Dominant overexpression of Sh3glb1, Tm4sf1 or Csf1 in chromosome 3 of TCs is mainly associated with tumour promotion in lung cancer, while most down-expression of Pde5 may be involved in the development of pulmonary fibrosis and other acute and chronic interstitial lung disease." (PMID 25278030, 2014). "Hence, we checked whether targeting TM4SF1 can restrain ARID1A-mutated lung cancer growth." (PMID 38229120, 2024). "Upregulated expression of TM4SF1 in lung cancer cells significantly increased their invasiveness in vitro and significantly decreased the survival time of xenograft mice, whereas silencing of TM4SF1 greatly inhibited tumor cell migration and invasion." (PMID 33015133, 2020). "Knockdown of a disintegrin and metalloproteinase-23 (ADAM23) increased the expression of TM4SF1 in lung cancer." (PMID 33015133, 2020). "In a phase I trial of mAb-L6, 19 patients with advanced breast, colon, ovarian, and lung cancers that highly expressed TM4SF1 were selected, and 18 patients were evaluable." (PMID 33015133, 2020). "Linear regression analysis revealed that TM4SF1 expression levels increased with malignancy in five human lung cancer cell lines (CL1-0, CL1-1, CL1-2, CL1-3, and CL1-5)." (PMID 33015133, 2020). "TM4SF1 was upregulated in both lung cancer cell lines and tissues, compared with 293 T epithelial cells." (PMID 31142317, 2019). "TM4SF1 was first discovered as an antigen for immunotherapy in lung cancer and its antibody MAb L6 showed a favorable binding properties and the encouraging clinical effect." (PMID 31142317, 2019). "With MTS, we analyzed the silencing of TM4SF1 on cell viability and cell growth in lung cancer cell lines, by western blot,the PCNA expression was downregulated by knocking down TM4SF1." (PMID 31142317, 2019). "To investigate the function of TM4SF1 in lung cancer cells, we transiently transfected A549 and H1299 cells with NC or siRNA-TM4SF1 and confirmed the knockdown of TM4SF1 by RT-PCR and western blotting." (PMID 31142317, 2019). "We report here that TM4SF1 regulates lung cancer chemo-sensitivity and apoptosis through the DDR1-activated AKT/mTOR signaling pathway." (PMID 31142317, 2019). "We then analyzed the effects of TM4SF1 silencing on lung cancer cell proliferation, migration and invasion in vitro." (PMID 31142317, 2019). "The wound healing assays also indicated that knockdown of TM4SF1 significantly inhibited lung cancer cell migration ability." (PMID 31142317, 2019). "Knockdown of TM4SF1 substantially inhibited tumor cell growth, migration, and invasion, and enhanced the chemo-sensitivity of the lung cancer cell lines A549 and H1299 to cisplatin and paclitaxel." (PMID 31142317, 2019). "In addition, TM4SF1 promoted the migration and invasion of lung cancer cells, and TM4SF1 expression regulated cell cycle arrest at the G2/M phase and promoted apoptosis in lung cancer cell lines A549 and H1299 cells." (PMID 33015133, 2020). "In lung cancer, TM4SF1 significantly regulated PCNA and reduced the viability of lung cancer cells." (PMID 33015133, 2020).
lung carcinoma (continued). "Furthermore, the silencing of TM4SF1 induced lung cancer cell apoptosis and arrested cells at the G2/M phase." (PMID 31142317, 2019). "Increased TM4SF1 protein expression can also increase the invasion ability of lung cancer cells, and an anti-TM4SF1 monoclonal antibody can significantly reduce the invasion ability of lung cancer cells." (PMID 30876464, 2019). "TM4SF1 may therefore serve as a potential biomarker for predicting the treatment response in lung cancer chemo-therapy." (PMID 31142317, 2019). "TM4SF1 was up-regulated in both lung cancer cell lines and tissues, thus suggesting that it may be a potential oncogene in NSCLC." (PMID 31142317, 2019). "We sought to understand the biological function of TM4SF1 in lung cancer, specifically whether it promotes or suppresses lung cancer development." (PMID 31142317, 2019). "TM4SF1 may serve as a biomarker of lung cancer outcome and prognosis." (PMID 31142317, 2019). "Thus, the expression of TM4SF1 may be a potential biomarker for early determination of lung cancer patient outcomes and treatment responses." (PMID 31142317, 2019). "With RT-PCR, we identified that TM4SF1 was up-regulated in the lung cancer cell lines A549, H1299, H1650, H460, H446, and H1466, compared with the epithelial cell 293 T cells, suggesting that it may potentially promote lung cancer." (PMID 31142317, 2019). "Overexpression of TM4SF1 and Csf1 in lung TCs may have a role in the development of lung cancer." (PMID 25278030, 2014). "Since TM4SF1 has the ability to regulate Akt signaling and ARID1A loss leads to the activation of Akt signaling in lung cancer cells, we thus examined whether PLAU and TM4SF1 interaction is involved in the activation of Akt signaling in ARID1A-deficient lung cancer cells." (PMID 38229120, 2024). "Through in vitro cell function analyze, we demonstrated that the silencing of TM4SF1 inhibited NSCLC cell proliferation, invasion, migration and especially enhanced lung cancer cells chemo-sensitivity to cisplatin and paclitaxel." (PMID 31142317, 2019). "In Transwell chamber assays, silencing of TM4SF1 markedly decreased the migration and invasion of lung cancer cells compared with wild-type and negative control cells (p < 0.001)." (PMID 31142317, 2019). "TM4SF1 was over-expressed in the lung cancer tissues relative to the adjacent non-tumor tissues in 21 out of the 25 pairs (84%), suggesting that it may be an oncogene in lung cancer." (PMID 31142317, 2019). "Furthermore, through real-time quantitative PCR, we quantified TM4SF1 expression in 25 paired lung cancer tissue and its related adjacent non-tumor tissues." (PMID 31142317, 2019). "Therefore, TM4SF4 functions in cancer, especially in lung cancer, have not been studied, although other members of the tetraspanin L6 family, such as TM4SF1 and TM4SF5, have been investigated as inducers of tumorigenesis." (PMID 25344917, 2014). "First, we examined TM4SF1 expression in NSCLC cell lines and paired lung cancer tissue and adjacent non-cancerous tissue, by using RT-PCR and semi-quantitative PCR, respectively." (PMID 31142317, 2019).